EIF3B (eukaryotic translation initiation factor 3 subunit B)
Diseases named in the same sentence as EIF3B in open-access papers (continued):
Sharing a sentence is not in itself a finding about the gene and the disease.
cholangiocarcinoma (1 paper, 2024). A carcinoma that arises from the intrahepatic biliary tree (intrahepatic cholangiocarcinoma) or from the junction, or adjacent to the junction, of the right and left hepatic ducts (hilar cholangiocarcinoma). "To delve into the underlying mechanism of EIF3B’s influence on cholangiocarcinoma, we further investigated its impact on PCNA." (PMID 38687509, 2024). "While Eukaryotic translation initiation factor 3 subunit B (EIF3B) has been implicated in the occurrence and development of various cancers, its specific roles in cholangiocarcinoma remain unexplored." (PMID 38687509, 2024). "Expression patterns of EIF3B in cholangiocarcinoma tissues and normal tissues revealed in immunohistochemistry analysis." (PMID 38687509, 2024). "Relationship between EIF3B expression and tumor characteristics in patients with cholangiocarcinoma." (PMID 38687509, 2024). "Depletion of EIF3B was shown to impede the progression of cholangiocarcinoma both in vitro and in vivo." (PMID 38687509, 2024). "EIF3B exhibited robust expression in cholangiocarcinoma, demonstrating a significant correlation with the pathological grade of cholangiocarcinoma patients." (PMID 38687509, 2024). "Immunohistochemical (IHC) analysis was employed to detect EIF3B/PCNA expression in cholangiocarcinoma." (PMID 38687509, 2024). "On the other hand, considering the enrichment of most genes in the cell cycle pathway and the recognized functional roles of P21 in cell cycle regulation, we postulated the involvement of theP21 pathway in EIF3B-mediated cholangiocarcinoma." (PMID 38687509, 2024). "Overall, our findings demonstrated that EIF3B was involved in cholangiocarcinoma development through targeting PCNA." (PMID 38687509, 2024). "We further evaluated the correlation between EIF3B with clinicopathological characteristics of patients with cholangiocarcinoma." (PMID 38687509, 2024). "The presented study revealed a significant upregulation of EIF3B in cholangiocarcinoma, demonstrating a strong correlation with the pathological grade of patients." (PMID 38687509, 2024). "IHC analysis revealed that EIF3B was abundant in cholangiocarcinoma tissues but rarely present in para-carcinoma tissues (P < 0.001)." (PMID 38687509, 2024). "In conclusion, our study elucidated that EIF3B played a pivotal role in promoting cholangiocarcinoma through the regulation of the PCNA and P21 pathways." (PMID 38687509, 2024). "In summary, these findings indicated the potential of EIF3B as a promising therapeutic target for cholangiocarcinoma." (PMID 38687509, 2024). "Taken together, we concluded that EIF3B promoted cholangiocarcinoma cell growth and migration, while suppressing cell apoptosis in vitro." (PMID 38687509, 2024). "We initiated our study by examining the role of EIF3B in the development and progression cholangiocarcinoma." (PMID 38687509, 2024). "Mechanistically, we identified Proliferating Cell Nuclear Antigen (PCNA) as a downstream gene of EIF3B, driving cholangiocarcinoma." (PMID 38687509, 2024). "The validation of the interaction between PCNA and EIF3B indicated that PCNA serves as a downstream factor regulated by EIF3B in the context of cholangiocarcinoma." (PMID 38687509, 2024). "Our results showed abundant EIF3B expression in both cholangiocarcinoma tissues and cell lines, exhibiting a correlation with pathological grade." (PMID 38687509, 2024). "To confirm the contribution of PCNA to EIF3B-mediated cholangiocarcinoma progression, we established RBE cell models involving singular overexpression of EIF3B, singular silence of PCNA, and concurrent EIF3B overexpression with PCNA silencing." (PMID 38687509, 2024). "In this section, our aim was to elucidate the roles of EIF3B in cholangiocarcinoma development." (PMID 38687509, 2024). "EIF3B expression levels in cholangiocarcinoma tissues and cells were assessed." (PMID 38687509, 2024).
cholangiocarcinoma (continued). "To investigate the mechanism behind EIF3B knockdown blocking cholangiocarcinoma progression, we conducted a PrimeView Human Gene Expression Array on shCtrl/shEIF3B-transfected HCCC-9810 cells, identifying 402 upregulated and 442 downregulated genes in the shEIF3B group." (PMID 38687509, 2024). "On this account, EIF3B might act as a potential promotor in the development cholangiocarcinoma development." (PMID 38687509, 2024). "Our findings underscored the potential of EIF3B as a therapeutic target for cholangiocarcinoma." (PMID 38687509, 2024). "Furthermore, modulation of EIF3B expression, either depletion or elevation, demonstrated the ability to inhibit or enhance cholangiocarcinoma cell survival and migration in vitro." (PMID 38687509, 2024). "As anticipated, the results demonstrated a downregulation of Bcl-2 and Survivin, along with an upregulation of caspase-3 upon EIF3B knockdown, implying that EIF3B might be involved in cholangiocarcinoma cell apoptosis through regulating these proteins." (PMID 38687509, 2024). "In addition, Kaplan-Meier survival analysis revealed that increased EIF3B expression predicted poor overall survival (OS) for patients with cholangiocarcinoma." (PMID 38687509, 2024). "Subsequently, we assessed the impact of EIF3B depletion on cholangiocarcinoma cell phenotypes." (PMID 38687509, 2024). "To further validate whether PCNA could reverse the inhibitory effects of EIF3B knockdown on cholangiocarcinoma, we conducted separate transfections of a PCNA overexpression plasmid and an EIF3B knockdown plasmid, as well as simultaneous transfections, in REB cells." (PMID 38687509, 2024). "The tumor-promoting impact of EIF3B was found to be mediated through PCNA, and the inhibition of PCNA not only suppressed the development of cholangiocarcinoma but also reversed the promotional effects induced by EIF3B overexpression." (PMID 38687509, 2024). "This shed light on a novel regulatory mechanism involving EIF3B, SYVN1, and PCNA in cholangiocarcinoma pathogenesis." (PMID 38687509, 2024). "Similar to EIF3B, PCNA levels were also abundant in cholangiocarcinoma, and knocking down PCNA impeded cholangiocarcinoma development." (PMID 38687509, 2024).
chronic gastritis (1 paper, 2019). Inflammation of the stomach that is chronic in nature. "In addition, the qRT-PCR results show that the eIF3b mRNA expression in chronic gastritis tissues was higher than that in normal gastric mucosal tissues." (PMID 31423012, 2019).
chronic myeloid leukemia (1 paper, 2025). "Additionally, in chronic myeloid leukemia, high EIF3B expression promotes cell proliferation and viability while suppressing apoptosis, thus facilitating the progression of the disease." (PMID 40435202, 2025).
colorectal cancer (1 paper, 2022). A primary or metastatic malignant neoplasm that affects the colon or rectum. "The significance of the EIF family member eIF-4E with perineural invasion was reported in colorectal cancer, and the correlation between EIF3B and PNI in HNSCC was first reported in this study." (PMID 35459206, 2022).
COVID-19 (1 paper, 2023). A disease caused by infection with severe acute respiratory syndrome coronavirus 2. "It was revealed that three hub CORGs (ENTPD6, CIB1, and EIF3B) had good diagnostic performance to discriminate COVID-19/MI and control samples (AUC > 0.75)." (PMID 37020555, 2023). "It is noted that two hub genes (CIB1 and EIF3B) had the significant change pattern in the sequencing findings and qRT-PCR results, emphasizing the critical genetic links of CIB1 and EIF3B between COVID-19 and MI." (PMID 37020555, 2023).
ductal breast carcinoma (1 paper, 2022). "In Finak’s dataset, EIF3B was overexpressed in invasive breast carcinoma versus normal tissue with a fold change of 3.280; as for ductal breast carcinoma, EIF3B only increased with a fold of 1.33, which suggested a higher expression of EIF3B was accompanied by tumor progression." (PMID 35040374, 2022).
gastritis (1 paper, 2019). Inflammation of the stomach. "Then, we performed a statistical analysis again and found that the mRNA expression of eIF3b was higher in Hp+ gastritis tissues than that in Hp− gastritis tissues." (PMID 31423012, 2019). "Moreover, the expression of eIF3b in Hp+ gastritis tissues was higher than the expression in Hp− gastritis tissues." (PMID 31423012, 2019).
head and neck squamous cell carcinoma (1 paper, 2024). A squamous cell carcinoma that arises from any of the following anatomic sites: lip and oral cavity, nasal cavity, paranasal sinuses, pharynx, larynx, and salivary glands. "Another study silenced eukaryotic translation initiation factor 3 subunit B (EIF3B), commonly associated with unfavorable head and neck squamous cell carcinoma (HNSCC) prognosis." (PMID 38392321, 2024).
Hyperammonemia (1 paper, 2023). An increased concentration of ammonia in the blood. "Shared DAP that were increased at both 6 and 24 h of hyperammonemia included Eif4b, Map4, Arpc1b, Eif3b, S100a4, Smad4, and Hist1h2bb." (PMID 37101412, 2023).
insulinoma (1 paper, 2025). "We show in mouse insulinoma MIN6-K8 cells exposed to fasting glucose levels that G3BP1 and its paralog G3BP2 colocalize to cytosolic condensates with eIF3b, phospho-AMPKαThr172 and Ins1/2 mRNA." (PMID 40355555, 2025).
laryngeal squamous cell carcinoma (1 paper, 2025). A squamous cell carcinoma that arises from the larynx. "The relative mRNA expression levels of EIF3B were quantitatively assessed in human nasopharyngeal epithelial cells (NP-69) and laryngeal squamous cell carcinoma (LSCC) cells (AMC-HN-8 and TU212) using qPCR." (PMID 40691141, 2025).
lentivirus infection (1 paper, 2021). Virus diseases caused by the Lentivirus genus. "EIF3B knockdown cell models were constructed by lentivirus infection." (PMID 33996561, 2021).
lung adenocarcinoma (1 paper, 2013). A carcinoma that arises from the lung and is characterized by the presence of malignant glandular epithelial cells. "EIF3B is a crucial part of the EIF3 complex that is implicated in tumor formation.Therefore, it is concluded that EIF3B plays a critical factor in enhancement of protein synthesis in lung adenocarcinoma." (PMID 23874428, 2013).
lymph node metastasis (1 paper, 2016). "Overexpression of EIF3B was associated with tumor depth, lymph node metastasis and advanced TNM stage." (PMID 27270324, 2016).
tumor (27 papers, 2012 to 2025). "The study highlighted the significance of EIF3B in tumor progression and implicated EIF3B as a promising candidate target for LSCC treatment." (PMID 40691141, 2025). "Specifically, the results of TCGA and online databases demonstrated that upregulated EIF3B was associated with poorer overall and advanced tumor progression." (PMID 35040374, 2022). "The expression of eIF3b, eIF3i, eIF3k and eIF3m was increased with the tumor grade, and was associated with poorer overall survival [All Hazard ratio (HR) > 1 and P < 0.05]." (PMID 31171919, 2019). "Collectively, EIF3B expression was significantly correlated with tumor pathological features, which may serve as a diagnostic marker." (PMID 40691141, 2025). "Upregulated EIF3B was associated with poorer overall and tumor progression." (PMID 35040374, 2022). "Furthermore, the Mann–Whitney U analysis was performed to explore the relationship between EIF3B expression and PC tumor characteristics, revealing a significant association between the expression of EIF3B and pathological grade (P < 0.01)." (PMID 33996561, 2021). "In addition, we have revealed the tumor-promoting function of eIF3b in ESCC in previous study, however, the underlying molecular mechanism remains elusive." (PMID 31481019, 2019). "To investigate the correlations between EIF3B expression and clinicopathological features, we employed statistical analysis and found that high expression of EIF3B was positively associated with tumor depth, lymph node metastasis and TNM stage, significantly (P < 0.05)." (PMID 27270324, 2016). "From Gene Expression Omnibus (GEO) database, we identified that EIF3B was upregulated in LSCC tissue samples (n = 9) compared with paired non-tumor tissue samples (n = 9)." (PMID 40691141, 2025). "Our data indicated that the expression level of EIF3B was positively correlated with age, T Infiltrate, lymphatic metastasis, tumor size, and stage." (PMID 40691141, 2025). "Our study identifies EIF3B as a critical oncoprotein in LSCC, with its overexpression linked to aggressive tumor behavior and poor prognosis." (PMID 40691141, 2025). "The high expression of EIF3B accounted for 45.5% of tumor tissues (n = 123), and only 2.4% of normal tissues (n = 41)." (PMID 40691141, 2025). "The total fluorescence intensity served as a surrogate marker for tumor burden, revealing that EIF3B overexpression intensified fluorescence intensity compared to the negative control (NC), whereas MAP2K2 knockdown diminished it." (PMID 40691141, 2025). "Accumulated evidence indicated that EIF3B is overexpressed in various tumors and is significantly related to poor prognosis as well as tumor development." (PMID 40691141, 2025). "After 21 days of continuous observation, mice with EIF3B overexpression exhibited significantly smaller tumor volumes, corroborated by lighter tumor weights compared to the control group." (PMID 40691141, 2025). "Previous research has focused primarily on downstream regulation of EIF3b, with limited understanding of its regulatory mechanisms in tumor progression." (PMID 39247811, 2024). "Through the use of shEIF3B-expressing lentivirus, we successfully silenced EIF3B and observed a consequential tumor suppression effect." (PMID 38687509, 2024). "These indicated that EIF3B is essential not only for cell proliferation and migration in vitro but also for efficient tumor growth in vivo." (PMID 38687509, 2024). "After 90 days, tumor tissues were harvested for IHC analysis, demonstrating a marked downregulation of EIF3B, PCNA and Ki-67 levels in the EIF3B knockdown group." (PMID 38687509, 2024). "Remarkably, PCNA overexpression effectively rescued the tumor-inhibitory effects induced by EIF3B knockdown, resulting in heightened proliferation and migration, alongside the inhibition of apoptosis." (PMID 38687509, 2024). "Overexpressed EIF3b in cholangiocarcinoma cells mediates tumor cell survival and migration by inhibiting PCNA ubiquitination." (PMID 39247811, 2024).
tumor (continued). "To further confirm that PUS1 increases EIF3b protein stability, we treated tumor cells with chlorhexidine (CHX), a protein synthesis inhibitor, while knocking down or overexpressing PUS1." (PMID 39247811, 2024). "The EIF3B-silenced cells demonstrated decreased invasion and migration capabilities, and the EIF3B knockdown group mice showed significantly decreased tumor volumes." (PMID 35459206, 2022). "The tumor volume in the EIF3B knockdown group was significantly decreased, thus supporting the oncogenic role of EIF3B in HNSCC." (PMID 35459206, 2022). "EIF3B knockdown inhibited the abilities of proliferation and migration of PC cells, promoted cell apoptosis in vitro, and suppressed the tumor growth in vivo." (PMID 33996561, 2021). "In silico, increased gene expression over all four tumor grades was determined for eIF3B, eIF3I, eIF3K and eIF3M." (PMID 33807050, 2021). "Eukaryotic translation initiation factor 3 subunit B (EIF3B) is necessary for tumor growth, which is an alternative therapeutic target for many cancers." (PMID 33996561, 2021). "The expression levels of EIF3B in PC tumor tissues and para-carcinoma tissues were determined by immunohistochemical staining." (PMID 33996561, 2021). "It was obvious that EIF3B expression was significantly up-regulated in tumor tissues compared with para-carcinoma tissues, which was also indicated by the statistical analysis (P < 0.001)." (PMID 33996561, 2021). "qRT-PCR was used to detect the expression of eIF3b in the tumour tissues, and the results show that the eIF3b mRNA expression in the experimental groups was inhibited." (PMID 31423012, 2019). "The tumour growth curve shows that the downregulation of eIF3b inhibited the growth of subcutaneous xenografts in nude mice." (PMID 31423012, 2019). "Some studies have suggested that eIF3b is involved not only in protein translation but also in cell proliferation, invasion, migration and tumour development." (PMID 31423012, 2019). "Eukaryotic translation initiation factors 3B (EIF3B) is considered to influence tumor proliferation, invasion, apoptosis and cell cycle, which act together to promote the progression of tumors." (PMID 27270324, 2016). "Furthermore, the relationship between EIF3B expression and tumor characteristics of clinical LSCC patients (n = 123) was analyzed." (PMID 40691141, 2025). "Moreover, EIF3B overexpression accelerated tumor growth in xenograft models, which was rescued by MAP2K2 knockdown." (PMID 40691141, 2025). "However, our study is the first to detail the specific role of TTC3 in EIF3b ubiquitination, providing new insights into the regulatory mechanisms of EIF3b in tumor progression." (PMID 39247811, 2024). "Together, our results implied that EIF3B could affect tumor progression by regulating the cell cycle and proliferation." (PMID 35040374, 2022). "All these illustrated that EIF3B was a tumor promoter of PC." (PMID 33996561, 2021). "Moreover, the decreased Ki-67 index detected in tumor sections in SW1990 cells showed that EIF3B knockdown inhibited the expression of Ki-67 (P < 0.01)." (PMID 33996561, 2021). "The expression of EIF3B was significantly up-regulated in tumor tissues and PC cell lines." (PMID 33996561, 2021). "In this study, we found that EIF3B expression was up-regulated in PC tumor tissues." (PMID 33996561, 2021). "Suppressing the expression of EIF3B or interrupting its signaling pathways may prevent or even reverse the process of tumor development." (PMID 33996561, 2021). "More importantly, we found that EIF3B knockdown made the growth of tumor slower in vivo." (PMID 33996561, 2021). "Levels of nine eIF3 subunits involving eIF3A, eIF3B, eIF3C, eIF3D, eIF3E, eIF3H, eIF3I, eIF3J, and eIF3M were significantly increased in cancer tissues, whereas the eIF3L expression level in tumours was independently decreased than that of normal tissues (p < 0.05)." (PMID 31885740, 2019).